BCR (BCR activator of RhoGEF and GTPase)
Diseases named in the same sentence as BCR in open-access papers (continued):
Sharing a sentence is not in itself a finding about the gene and the disease.
leukemia (continued). "Two forms of the BCR-ABL oncogene encode the fusion proteins BCR-ABLp190 and BCR-ABLp210 that are associated with different forms of leukaemia." (PMID 32213936, 2020). "So far, it is hard to see how the two forms of BCR-ABL forms clearly associate with different leukaemias and there are two possibilities." (PMID 32213936, 2020). "We have identified the transcription factors STAT5A/B as critical nodes in the signaling network downstream of the leukemia-associated BCR/ABL oncogene." (PMID 30679796, 2019). "Here, we investigated the role of STAT5 isoforms in BCR/ABL+ leukemia, a disease that ceases upon combined loss of STAT5A and STAT5B." (PMID 30679796, 2019). "Our current findings disclose that these genetically homogeneous leukemia cells, in terms of BCR/ABL, KIT or FLT3 mutations, are epigenetically heterogeneous and can be distinguished by overexpression of FTO and reduction of m6A methylation." (PMID 30297871, 2018). "We found that patients with IL7RhighSH2B3low expression have features of high-risk leukemia, unfavorable outcome and a high rate of both Ikaros deletion (60%) and BCR-ABL fusion (75.1%)." (PMID 27322554, 2016). "CML is a type of leukemia that is caused by the BCR-ABL oncogene which is due to chromosomal rearrangement." (PMID 27760149, 2016). "We thus decided to inventory, among the Ph+ leukemia patients referred to our laboratories for routine BCR-ABL KD analysis, all those who had acquired mutations eliciting resistance to second-line dasatinib or nilotinib therapy." (PMID 26980736, 2016). "The hallmark of Philadelphia chromosome positive (Ph+) leukemia is the BCR/ABL kinase, which is successfully targeted by selective ATP competitors." (PMID 25919613, 2015). "Our evaluation of the role of the PI3K pathway in leukemic cell growth and survival focused initially on BCR-ABL expressing leukemias, as PI3K signaling has been strongly implicated in malignant transformation and development of TKI-resistance in Ph+ ALL." (PMID 24244612, 2013). "The most specific leukemia antigens are peptides from aberrant proteins created by mutations or translocations only present in leukemia cells, such as the BCR/ABL1 tyrosine kinase in CML." (PMID 24427158, 2013). "c-Abl is encoded by the ABL1 gene whose translocation to the BCR gene results in the BCR–Abl fusion protein, known to be involved in the development of some leukaemias." (PMID 22075945, 2012). "For example, epigenetic silencing of miR-203 has been implicated in the regulation of the BCR-ABL gene in leukemia." (PMID 22053178, 2011). "Leukemia is a heterogeneous disease commonly associated with recurrent chromosomal translocations that involve tyrosine kinases including BCR-ABL, TEL-PDGFRB and TEL-JAK2." (PMID 22204395, 2011). "Until now, the biology of Ph+ leukemia has been strictly limited to der22-encoded BCR/ABL and the related signal transduction pathways." (PMID 19876398, 2009). "Several studies have reported the presence of leukemia-lymphoma-associated fusion genes (e.g., BCR/ABL1, IGH/BCL2, TCRβ/γ) in normal individuals." (PMID 21637673, 2009). "The constitutively activated BCR-ABL tyrosine kinase fusion protein which has been shown to be an essential step in the pathogenesis of Philadelphia chromosome (Ph)-positive leukemias also associates with PI3K." (PMID 19384426, 2007). "The fusion of BCR with ABL oncogene is a leukemia-associated chromosomal translocation which resulted in the fusion proteins p120 and p190 that lacked the RhoGAP domain of BCR." (PMID 17284314, 2007). "Under these circumstances, direct induction of the mutations into the intrinsic BCR::ABL1 gene in human leukemia cells could be another useful model system." (PMID 39872583, 2024). "In these circumstances, BCR::ABL1 could be considered a CHOP mutation likely to progress to overt leukemia subsequent to a variable latency period." (PMID 37895120, 2023).
leukemia (continued). "Herein, we explored the therapeutic potential of pterostilbene on various hematological malignancies, especially in BCR/ABL+ leukemia, and also explored the underlying molecular and cellular mechanism by which pterostilbene exerts its effects on these leukemic cells." (PMID 35027628, 2022). "Oncogenic forms of ABL1, in particular the BCR-ABL1 fusion gene with different breakpoints in BCR gene, are well-recognized for their pathogenic role in leukemias, including chronic myeloid leukemia (CML), some forms of acute myeloid leukemia (AML), and acute lymphoblastic leukemia (ALL)." (PMID 34867354, 2021). "Since multiple targeted tyrosine kinase inhibitors have been developed to specifically target the BCR/ABL mutation in leukemia/lymphoma patients, diagnosis of the subtype of the leukemia/lymphoma with the BCR/ABL mutation will be very important in regarding the patient's treatment." (PMID 34115047, 2021). "As compound mutations pose a new threat by causing resistance to all FDA approved tyrosine kinase inhibitors in BCR-ABL+ leukemias, our study opens a new direction for in vitro characterization of novel BCR-ABL compound mutations and their resistant to second generation and third generation TKIs." (PMID 33369447, 2020). "Importantly, Bisindolylmaleimide IX is effective in treating CML-like leukemia caused by BCR-ABL or T315I mutant BCR-ABL." (PMID 27564101, 2016). "By altering Ph+ leukemia cell interactions with the microenvironment, we may increase their susceptibility to therapy targeting BCR/ABL." (PMID 24860788, 2014). "Besides JAK2, STAT5 can be persistently activated in leukemias by the BCR/ABL tyrosine kinase and mutations in c-KIT or FLT-3." (PMID 23565285, 2013). "The long latency, especially of p96ABL/BCR-positive leukemia, may be attributed to the need for additional mutations." (PMID 19876398, 2009). "Studies regarding TKI resistance in leukemia have mostly centered on cancer genetic alterations, for example, acquired mutations (which happen in about 1/3 of progressive cases) in the kinase domains of BCR::ABL1 that reduce or even fully impair TKIs’ binding to ABL kinase." (PMID 41203598, 2025). "In previous studies from our group, we have provided evidence that at least a fraction of T cells in patients with CLL may specifically recognize leukemia-associated antigens, with the clonotypic BcR IG expressed by the malignant cells emerging as a potential source of neoepitopes selecting T cells." (PMID 36816924, 2023). "Interestingly, the integral role of BIM in promoting apoptosis in response to molecular targeted therapies has been determined in BRAF-mutant colorectal cancer cells, BRAF-mutated melanoma cells, BCR–ABL-positive leukemia cells, and EML4-ALK-positive NSCLC cells." (PMID 36553449, 2022). "Specific to cancers, TOPK is regulated by protein phosphatase 2A (PP2A) and BCR/ABL in leukemia and enhances cell proliferation, indicating that it may be a target of BCR/ABL, and has been associated with HTLV-1-transformed T-cell lines and ATLL-derived T-cell lines." (PMID 34066486, 2021). "The b3a2 TCR specifically recognizes MHC class II and was originally derived from a CD4+ T cell targeting the BCR-ABL fusion protein in leukemia." (PMID 41484912, 2026). "In particular, JAK2 fusion partners have been identified alongside PCM1 — including BCR and ETV6— in both B- and T-lineage leukemias, further complicating diagnostic classification and therapeutic decision-making." (PMID 41530508, 2026). "In leukemia, TOPK is regulated by PP2A and BCR/ABL, where PP2A associates with and dephosphorylates TOPK, while BCR/ABL upregulates its expression." (PMID 41362722, 2026). "Resistance to tyrosine kinase inhibitors (TKIs) remains a major challenge in breakpoint cluster region (BCR)::Abelson 1 (ABL1)-driven leukaemias." (PMID 41696976, 2026). "As described in the literature, the BCR::FGFR1 translocation has been observed in cases with mixed phenotype leukemia." (PMID 41180818, 2025).
leukemia (continued). "The broad epigenetic modulation of martinostat has therapeutic potential beyond BCR–ABL–driven leukemia, such as that involving ETV6-ABL1 or NUP214-ABL1 fusion proteins." (PMID 40671124, 2025). "The BCR/ABL fusion protein induces IL-6 expression in leukemia stem cells, and targeting IL-6R induces apoptosis in Philadelphia chromosome-positive acute lymphoblastic leukemia cells." (PMID 41293238, 2025). "To assess the effects of Prmt1 loss on the propagation of leukemia, we transduced BM cells from 5‐FU‐treated Prmt1fl/fl; Cre‐ERT2 or Prmt1fl/fl mice with BCR‐ABL‐GFP retrovirus and transplanted them into sublethally irradiated recipients." (PMID 39668478, 2025). "CML leukemia stem cells (LSCs) can be considered as drug-resistant cells, which is BCR/ABL kinase-independent." (PMID 40346054, 2025). "Experimental mouse models reveal that high-level expression of BCR::ABL alone is insufficient to induce leukemia, whereas co-expression with Setbp1, Hoxa10 or Hoxa9 produces aggressive leukemia within 3 weeks." (PMID 41179655, 2025). "Dasatinib, a potent SRC and SFK tyrosine kinase inhibitor, is approved for treating certain leukemia types, primarily due to its effectiveness against BCR-ABL fusion proteins that drive these malignancies." (PMID 40598793, 2025). "The IL7R and pre-BCR signaling pathways intersect at several key points, affecting B cell development and leukemia." (PMID 40709996, 2025). "To extend these approaches to pediatric leukemias, we profile samples from patients diagnosed with one of two well-defined subtypes: BCR::ABL1-like and ETV6::RUNX1 B-ALL, which have distinct prognoses, known signaling pathways, and treatment approaches." (PMID 40832224, 2025). "It remains to be determined how and to which extent CDK6 inhibition alters metabolism of cancer cells and which role CDK6 specifically plays in this context in BCR::ABL1+ leukemia." (PMID 39966356, 2025). "Sequencing revealed a rare BCR transcript with an exon 6 breakpoint corresponding to e6a2 transcripts, which has thus far been reported in only 26 cases of leukemias." (PMID 39846605, 2025). "The synergistic anti-leukemic effect of tyrosine kinase inhibitors combined with venetoclax has been previously demonstrated in both preclinical and clinical settings for BCR::ABL1-positive leukemias." (PMID 40858806, 2025). "A literature review conducted on the treatment of leukemia with the BCR::FGFR1 translocation underscores the importance and effectiveness of allogeneic hematopoietic SCT as a primary therapy to achieve molecular remission in acute leukemia." (PMID 41180818, 2025). "Established asciminib-resistant (ASCI-R) clones of KCL-22 cell line (n = 8) were analyzed using Next Generation Sequencing (NGS) to identify somatic mutations in SH3, SH2, and kinase (KD) domains of BCR::ABL1 and in 62 selected leukemia-associated genes." (PMID 40858806, 2025). "Then, we found that LAPTM4B is expressed primarily in stem cells at single-cell level in leukemia, and highly expressed in BCR/ABL subtype of B-ALL, and upregulated stem cell pathway in Ph+ B-ALL." (PMID 40092987, 2025). "We measured the rate at which the leukemia marker BCR::ABL1 decreased within the first three months and compared it with the long-term treatment outcome." (PMID 41463243, 2025). "In this study, we performed proteomic and phosphoproteomic profiling of samples collected at diagnosis and remission from pediatric leukemia patients with one of two subtypes of B-ALL: BCR::ABL1-like (Ph-like) and ETV6::RUNX1." (PMID 40832224, 2025). "Aside from its growth inhibition of BCR-ABL translocation-positive leukemias, GNF-7 has been shown to have a variety of effects in several other model systems." (PMID 40805174, 2025). "For example, our prior work showed that CD9 activates the PI3K/Akt pathway to drive leukemia progression and chemoresistance in BCR::ABL1+ cells." (PMID 38001171, 2024).
leukemia (continued). "In human Ph+ leukemia cell lines, amplification of the BCR::ABL1 gene is generally observed, and TCCS has four alleles of the BCR::ABL1 gene." (PMID 39872583, 2024). "Together, these data indicate that the cell phenotype with pre-BCR and pre-B fate TF expression is present in leukemia patient-derived cells." (PMID 38822412, 2024). "The Philadelphia chromosome and the creation of the BCR-ABL fusion gene is one of the most famous translocations directly involved in oncogenesis of leukemia." (PMID 39457371, 2024). "In this study of patients with B-ALL, we show that, in the context of risk-directed therapy and the use of tyrosine kinase inhibitors (TKI) for patients with BCR::ABL1 leukemia, unfavorable subtype groups are independently prognostic." (PMID 39606455, 2024). "CML was the first disease to have a targeted therapy, with the development of imatinib, a TKI that specifically targets the BCR::ABL1 protein in leukemia cells." (PMID 39450252, 2024). "Philadelphia chromosome positive (Ph+) leukemia is a malignant clonal disease derived from hematopoietic stem cells, which is characterized by the expression of BCR-ABL fusion protein possessing strong tyrosine kinase activity." (PMID 38741123, 2024). "Disease relapse upon BCR::ABL1 TKI treatment discontinuation or the development of treatment resistance in CML can occur due to the persistent leukemia stem/progenitor cell population." (PMID 39063200, 2024). "Drug resistance to tyrosine kinase inhibitors (TKIs), due to BCR::ABL1 mutations and residual leukemia stem cells (LSCs), remains a major challenge in CML treatment." (PMID 37880985, 2024). "This advanced disease stage exhibits clonal, genomic, and molecular heterogeneity, often featuring additional chromosomal aberrations and mutations in the BCR::ABL1 kinase domain and/or other leukemia-related genes." (PMID 38615117, 2024). "Thus, contrary to currently held views that stemness features critically underlie drug resistance in KMT2A-r leukemias, we found that upon targeting their cell cycle control vulnerability, the drug-tolerant cells corresponded to a more differentiated phenotype with expression of pre-BCR and BCL6." (PMID 38822412, 2024). "The specificity of VTP-50469 against KMT2A-rearranged leukemia was further reinforced by its inability to significantly delay the progression of a BCR::ABL1 fusion-positive ALL PDX." (PMID 39510293, 2024). "Phospho flow cytometry and apoptosis assays were performed to assess the functional effects of monobody translocation into BCR:ABL1-expressing leukemia cells." (PMID 39415233, 2024). "Concurrently, Dovitinib, targeting FLT1, EGFR, FLT3 and KIT, acts as a EGFR inhibitor and FLT3 inhibitor, with previous research showing Dovitinib showed treatment efficacy in naïve and imatinib-resistant BCR::ABL(+) leukemia cells." (PMID 39247833, 2024). "In our previous studies on BCR::ABL1-positive leukemias, we defined “CML-like” leukemias, diagnosed as ALL but exhibiting BCR::ABL1 fusion in multipotent, not fully leukemic progenitors, biologically resembling CML in lymphoid blast crisis." (PMID 38970095, 2024). "Despite this progress, leukemia stem cells in CML can persist independently of BCR-ABL, leading to resistance to imatinib and presenting a major clinical challenge." (PMID 39202551, 2024). "Here, we report a new leukemogenic process in which RAPSYN and BCR-ABL co-occur in Ph+ leukemia, and RAPSYN mediates the neddylation of BCR-ABL." (PMID 38865175, 2024). "Here, a murine transplantation model yielded data supporting the potential of PARPi for the treatment of BCR/ABL1-positive leukemia." (PMID 37165001, 2023). "BCR::ABL+, as well as BMI1+ cells alone, were not able to introduce leukemia within 25 weeks post-transplantation, whereas 50% of BCR::ABL+/BMI1+ mice succumbed to leukemia within weeks." (PMID 38201282, 2023).
leukemia (continued). "Our data showed that increased expression of ZFX had the tendency to accelerate the generation of leukemia induced by BCR/ABL." (PMID 37864206, 2023). "CLL is a leukemia in which constitutive signaling through the BCR pathway is important to malignant B-cell survival." (PMID 36711753, 2023). "If BCR::ABL1 is undetected (molecularly undetectable leukemia), the number of reference gene transcripts in the same volume of cDNA used to test for BCR::ABL1 indicates the sensitivity for that particular sample." (PMID 37794101, 2023). "AMLs carrying the BCR::ABL1 rearrangement have often been described as de novo leukemias and, more rarely, as a secondary event during disease relapse." (PMID 37895120, 2023). "Death from BCR/ABL1-mediated leukemia was observed in sham-treated mice at 1 month post-transplantation." (PMID 37165001, 2023). "The relationship between NF-κB and BCR/ABL (ABL1) is long-lasting in Philadelphia positive leukaemia." (PMID 37098530, 2023). "Leukemia in BCR/ABL1 Tg mice developed 6 months after birth, after which time the mice started to die18." (PMID 37165001, 2023). "We will also evaluate the current evidence for treatment of BCR::ABL1-positive leukaemias, including TKI discontinuation in optimally responding CP-CML patients." (PMID 38550948, 2023). "In vitro experiments have shown that bosutinib has antiproliferative activity against multiple BCR::ABL1-positive leukemia cell lines as well as the ability to block BCR::ABL1 phosphorylation at sub-micromolar concentrations." (PMID 38004514, 2023). "In leukemia, K562 leukemia cells transfected with a hsa-miR-203 plasmid were sensitized to arsenic trioxide by inducing apoptosis and reducing BCR/ABL gene expression levels." (PMID 37124518, 2023). "The patient-derived xenograft (PDX) mice succumbed to their leukemia at a median of 76 and 78 days (p = 0.0207 and p = 0.0295, respectively, compared with the BCR::ABL1 control with a median survival of 278 days)." (PMID 37483494, 2023). "We further employed these lyophilized exosomes to deliver tyrosine kinase inhibitors (TKIs) to the Ph+ leukemia established cell line (K562) and BCR-ABL-engineered murine cells (Ba/F3-P185)." (PMID 37445655, 2023). "Consistent with this role, multiple leukemic cell lines display increased CaMKII expression and autophosphorylation in the presence of background leukemia drivers, such as BCR-ABL." (PMID 38117861, 2023). "We have previously shown that GPR34/PI3K/AKT and GPR34/PI3K/ERK play important roles in proliferation, apoptosis, and migration in gastric cancer and BCR/ABL-positive leukemia." (PMID 34997428, 2022). "Confirming that our recipient mice indeed died of leukaemia, BCR::ABL1 transcripts were detectable in the peripheral blood of recipient mice but not controls (left)." (PMID 36536477, 2022). "The targeting of BCR-ABLp210 to the bone marrow hematopoietic stem and progenitor cells, via stem cell antigen (Sca1)-BCR-ABLp210, led to a leukemia resembling human chronic phase CML." (PMID 36362357, 2022). "The translocation contributes to the proliferation of leukemia cells, and when the BCR-ABL tyrosine kinase was activated on the Ph chromosome, it initiates disease development in three phases." (PMID 35528614, 2022). "Consideration is given to the influence of BCR-ABLp210 expression on the behavior of CML leukemia stem cells (LSCs) that give rise to the chronic phase of disease, and why the behavior of these cells is very different to that of HSCs." (PMID 36362357, 2022). "For the tet-off BCR-ABLp210 transgenic model and when BCR-ABLp210 expression was shut off, CML LSCs persisted in vivo and upon re-expression of BCR-ABLp210 they were able to initiate leukemia in secondary recipients." (PMID 36362357, 2022). "We also found that BPF targeted not only leukemia cells caused by BCR-ABL, but also leukemia cells expressing gatekeeper mutation-harbored BCR-ABL through these pathways." (PMID 35054935, 2022).